IRS4 (insulin receptor substrate 4)
Diseases named in the same sentence as IRS4 in open-access papers (continued):
Sharing a sentence is not in itself a finding about the gene and the disease.
cancer (22 papers, 2009 to 2025). A tumor composed of atypical neoplastic, often pleomorphic cells that invade other tissues. "IRS4 has been implicated in the progression of many cancers by maintaining pro-survival PI3K/Akt signalling." (PMID 40052110, 2025). "We used the name of the protein that it encodes “(IRS-4 or IRS4)”, or the combination of these terms with the word “(cancer)” or “(human)”, for searches." (PMID 37760618, 2023). "This pilot study, in conjunction with recent research, presents IRS-4 as a notable protein implicated in the development of cancer." (PMID 34071030, 2021). "IRS-4 is increasingly associated with cancer pathogenesis and hyperplasia." (PMID 30410539, 2018). "We analyzed IRS4 mRNA expression in a panel of 298 cancer cell lines, in order to determine whether high levels of IRS4 expression is associated with certain types of cancers." (PMID 24039912, 2013). "In NSCLC, IRS4 is overexpressed, promoting cancer progression via the PI3K/Akt and Ras-MAPK pathways and leading to resistance against EGFR-TKIs like gefitinib." (PMID 41219748, 2025). "In this paper, we collected data about the molecular mechanisms that explain the relevance of IRS4 in the development of cancer and identify IRS4 differences that distinguish it from IRS1 and IRS2." (PMID 37760618, 2023). "IRS4 is the least studied of this family, and its expression has recently been shown to be increased in many types of cancer." (PMID 37760618, 2023). "IRS-4 is an adaptor protein acting as a constitutive activator of critical cell transduction pathways in cancer, leading to the activation of the PI3K/Akt pathway collaborating with the actions of the human epidermal growth factor receptor 2 (HER2)." (PMID 35743985, 2022). "Upregulated IRS4 was detected in various cancer cell lines, and high phosphatidylinositol triphosphate level was also identified." (PMID 36686473, 2022). "The complete sequencing of 7416 and 1220 human cancer genomes revealed the deregulation of IRS-4 gene expression at the transcriptional level, which has been associated with a lower overall survival of patients in several types of cancer." (PMID 34577545, 2021). "PCNA, Ki-67, and pH3 are well accepted cancer biomarkers, thus, we decided to compare IRS-4 expression pattern with those of the three proteins using immunohistochemistry methods." (PMID 34071030, 2021). "In two independent genome-wide association studies (GWAS) using DNA from 7416 and 1220 donors of different cancer types, IRS-4 has been identified as one of the best candidates involved in the promotion of carcinogenesis." (PMID 34071030, 2021). "Recently, the complete sequencing of 7416 and 1220 human cancer genomes revealed the deregulation of IRS-4 gene in cancer cells; furthermore, the data situate IRS-4 in a tumor growth-promoting role." (PMID 34071030, 2021). "In this context, the DNA sequencing studies of 7,416 human cancers of different tissular origin found very frequent deletions in cis-regulatory regions of the IRS-4 gene and it has been established as an oncogenic driver." (PMID 30410539, 2018). "In the present study, we observed that IRS-4 overexpression in HepG2 and RKO cancer cells is associated with the activation of IGF-1 receptor signalling pathways in the absence of extracellular ligand." (PMID 30410539, 2018). "Here, we show that while IRS4 expression is low in most cancer cell lines, IRS4 mRNA and protein levels are markedly elevated in certain cells including the NCI-H720, DMS114, HEK293T and HEK293AAV lines." (PMID 24039912, 2013). "Together, these findings suggest IRS4 as a potential therapeutic target for cancers with high expression of this protein." (PMID 24039912, 2013). "Our results also imply that chronic β2-pS184 dephosphorylation in cancer cells (perhaps arising from sustained periods of low mTORC1 activity) contributes to survival and growth by providing a safeguard mechanism to preserve mTORC1 signalling through IRS4/Akt." (PMID 40052110, 2025).
cancer (continued). "Moreover, its expression is triggered in several types of cancer and in benign neoplasm, indicating an important role for IRS4 in cell proliferation-related processes." (PMID 37760618, 2023). "Knowledge of the role played by IRS4 in cancers at the molecular level, specifically as a platform for oncogenes, may enable the identification and validation of new therapeutic targets." (PMID 37760618, 2023). "Increased IRS4 expression in cancer cells may be due to changes in the regulatory region of the gene or increased chromosomal aberrations." (PMID 37760618, 2023). "The assessment of the IRS-4 in cancer biopsies could be of interest to carry out a personalized treatment with ActD." (PMID 34577545, 2021). "In recent times, the spectrum of cancer types in which IRS-4 is involved is increasing." (PMID 30410539, 2018). "This suggests that IRS4-induction, leading to drug resistance, may also frequently occur in patients treated with these anti-cancer drugs." (PMID 27876799, 2016). "Thus, targeting this pathway, possibly through IRS4 modulation, could help counteract therapeutic resistance in cancer." (PMID 41219748, 2025). "High IRS4 levels in cancer cells activate the PI3K/Akt/mTOR pathway, and experimental knockdown of IRS4 significantly decreases pathway proteins, suggesting its potential regulation in ULM." (PMID 40867239, 2025). "Given the differences between IRS1/2 and IRS4 at the molecular level, knowledge of the signaling pathways controlled by IRS4 may enable the design of new drugs for the treatment of cancer without causing deleterious effects on the regulation of insulin and/or IGF1 signaling cascades." (PMID 37760618, 2023). "The aim of the present study was to evaluate the effect of IRS-4 on IGF-1 receptor pathway and its impact on procaspase 3 and PARP expression in RKO and HepG2 cancer cell lines." (PMID 30410539, 2018). "We then collected 27 cell lines, including four cancer cell lines with the highest mRNA expression levels, and checked for the expression of IRS1, IRS2 and IRS4 proteins by Western blotting." (PMID 24039912, 2013). "Despite the lack of knowledge on IRS4, it has been reported that some cancers and benign tumors are characterized by high levels of IRS-4 expression." (PMID 37760618, 2023). "A series of assays were applied to assess the possible changes in cancer cell fitness in the absence of IRS4." (PMID 35550247, 2022). "Our findings also indicate that high expression of IRS4 has a significant role in PI3K signalling and therefore could be exploited to target this pathway in certain types of cancer." (PMID 24039912, 2013). "Our results caution that IRS4 expression is a potential off-target effect of retroviral delivery of genetic material into cells, and that high IRS4 levels identified in certain cancer cells can drive signalling via PI3K even in the absence of growth factors." (PMID 24039912, 2013). "Following phosphorylation, the affinity between IRS4 and the PI3K regulatory subunit PIK3R2 markedly increases, thereby promoting sustained activation of the PI3K-AKT signaling pathway and providing a continuous supply of proliferation signals for cancer cells." (PMID 41219748, 2025). "In sum, the data implicating IRS-4 in cancer cell proliferation in conjunction with the widespread prevalence of HCC led us to develop this pilot study, using both patient samples and experimental conditions in vitro, to unravel the possible role of IRS-4 in liver carcinogenesis." (PMID 34071030, 2021). "Moreover, IRS4 may also prove to be of wider clinical relevance as biomarker for PI3K/AKT pathway-dependent breast and other cancers." (PMID 27876799, 2016). "In this study we show that while expression of IRS4 is generally low in the studied panel of cancer cell lines, it is high in NCI-H720, DMS114, HEK293T and HEK293AAV cells and that PI3K signalling in these cell lines relies on IRS4, but not IRS1." (PMID 24039912, 2013).
tumor (16 papers, 2009 to 2024). "10/157 (6%) of the tumours showed an elevated IRS4 microarray signal, which was associated with poor overall survival (P=0.0481, log-rank test)." (PMID 27876799, 2016). "A general theme arises from these studies; IRS-1 and IRS-4 are most often associated with tumor growth and proliferation and IRS-2 is most often associated with tumor motility and invasion." (PMID 19534786, 2009). "The expression of several race-associated genes was also dependent on the MED12 mutation status of the tumor, being higher (FRAT2, TNFRSF19, ACP7, IRS4, PLEKHG4B, KRT17, SLN, and ZNF703) or lower (CAV2) in the mutated specimens compared with wild-type tumors." (PMID 37686244, 2023). "Compared to mice injected with OVCAR-5 IRS4-KO cells rescued with WT IRS4, we observed significantly delayed tumor formation in mice injected with OVCAR-5 IRS4-KO cells with an empty vector." (PMID 35550247, 2022). "The percentage of tumor cells with nuclear IRS-4 was 69.9 ± 3.2%, followed by nuclear PCNA 52.1 ± 7.8%, nuclear Ki-67 6.1 ± 1.1%, and finally pH3 with only 1.3 ± 0.2%." (PMID 34071030, 2021). "To date, our results suggest that IRS-4 behaves like cyclin D1 and Ki-67, both of which are robust markers of tumor proliferation." (PMID 34071030, 2021). "As we have observed in HepG2 and RKO, to a lesser extent, the overexpression of IRS-4 in tumoural tissue was accompanied by the increase in procaspase 3 and PARP with respect to normal tissue." (PMID 30410539, 2018). "Additionally, we compared IRS-4 expression by immunoblot in two normal human liver samples, from tissue adjacent to the tumor, with the corresponding results of IRS-4 levels in HepG2, HuH 7, and Chang cells." (PMID 34071030, 2021). "In this regard, the effect of IRS-4 on procaspase 3/caspase 3 expression levels may play a decisive role in tumour progression." (PMID 30410539, 2018). "Hence, clinical trials with selective enrolment are needed to shed more light on the clinical benefits of combined HER2 and PI3K/AKT/mTOR targeted therapy in tumours with PI3K/AKT pathway hyperactivation, including IRS4+ tumours." (PMID 27876799, 2016). "One may consider treating HER2+ tumours expressing high levels of IRS4 with drugs targeting PI3K, AKT and/or mTOR in combination with HER2-targeted therapy." (PMID 27876799, 2016). "Importantly, we observed a significant reduction in NMuMG-ErbB2 tumour growth (P=8.75 × 10−3, Welch's t-test), whereas tumours from cells additionally expressing Irs4 were unaffected by Lapatinib treatment." (PMID 27876799, 2016). "Indeed, we found that co-expression of Irs4 and ErbB2 in mammary epithelial cells synergistically accelerated tumour growth due to their activity in complementary oncogenic pathways: the PI3K/AKT and MAPK/ERK pathways, respectively." (PMID 27876799, 2016). "From these studies and from a screen performed in mice transgenic for activated rat ErbB2 (GJI, MB, ERMB, JH, unpublished data), we obtained MMTV proviral insertion data from a total of 1,132 tumours, of which 35 (3.1%) had insertions that map in the Irs4-locus on the X-chromosome." (PMID 27876799, 2016). "From the 31 tested triple-negative tumours, 9 (29%) could be scored as IRS4 positive and four (13%) of these as highly positive." (PMID 27876799, 2016). "IRS-4 could be involved in this process, favoring tumor proliferation in certain areas and decreasing the invasive capacity on the invasive front of the tumor, which could explain the phenomenon of patients with a lower proportion of IRS-4 and Ki-67 having a greater number of foci." (PMID 34071030, 2021). "Consistently, ectopic expression of IRS4 in HEY and OVCAR-8 cells significantly accelerated tumor formations compared to parental controls." (PMID 35550247, 2022).
tumor (continued). "As we noticed IRS4 expression particularly in HER2+ tumours and found IRS4 to induce constitutive PI3K/AKT pathway activation, we investigated the involvement of IRS4 with regard to sensitivity to therapeutic agents." (PMID 27876799, 2016). "Therefore, it may be useful to investigate these aspects in IRS4-induced tumours in the future." (PMID 27876799, 2016). "In the current study, tumor growth was significantly suppressed in the absence of IRS4, and re-expressing phosphorylation-defective mutant of IRS4 failed to rescue proliferation rate of the tumor cells." (PMID 35550247, 2022). "The antibody used was quite specific for IRS4, since no signal was observed in xenograft tumor sample derived from IRS4-KO OVCAR-5 cells rescued with an empty vector." (PMID 35550247, 2022). "Interestingly, the markers studied (IRS-4, PCNA, Ki-67, or pH3) increased significantly in the group G2 with respect to G1 group, which suggests a relation with tumor grade." (PMID 34071030, 2021). "However, in this case one gene (Col4a5), functions as a hotspot for retroviral integrations that induce expression of another distal gene (Irs4), without affecting the expression of Col4a5 itself in any tumor analyzed (and data not shown)." (PMID 24886479, 2014). "IRS4-positive tumours were enriched among triple-negative/basal-like (6/25, 24%) and HER2-enriched tumour subtypes (2/18, 11%), whereas virtually absent in the luminal A (1/67, 1%) and B (1/47, 2%) subtypes (P=2.68 × 10−3, Pearson's χ2-test)." (PMID 27876799, 2016).
infection (1 paper, 2013). The state of being infected such as from the introduction of a foreign agent such as serum, vaccine, antigenic substance or organism. "Previously, IRS4 levels were shown to be elevated after adenovirus 5 E1A infection and transfections of cells." (PMID 24039912, 2013). "We also found that IRS4 expression is strongly induced upon infection of HEK293 cells with retroviral particles and subsequent selection with puromycin." (PMID 24039912, 2013).
kidney diseases (1 paper, 2021). "Furthermore, in our study the creatinine values were normal and there was no sign of kidney dysfunction in the individuals with IRS4 mutation and the family history was negative for any kidney diseases." (PMID 34093435, 2021).
IRS4 also shares sentences with these, for which no sentence is quoted: acute lymphoblastic leukemia (3 papers); schizophrenia (2); benign tumors (1); central congenital hypothyroidism (1); Cognitive impairment (1); Ductal Carcinoma (1); gynecological tumors (1); Hypertension (1); Lobular Carcinoma (1); lung squamous cell carcinomas (1); neurodegenerative disease (1); ovarian clear cell adenocarcinoma (1); prostate carcinoma (1); small cell lung carcinoma (1); T-cell lymphoma (1).